PTPRN (protein tyrosine phosphatase receptor type N)
Diseases named in the same sentence as PTPRN in open-access papers (continued):
Sharing a sentence is not in itself a finding about the gene and the disease.
lung carcinoma (1 paper, 2021). "Although PTPRN could be a new marker for detecting neuroendocrine differentiation in lung cancer, the potential relationship between PTPRN and on EMT is still unclear." (PMID 34150744, 2021). "First, we found the impact of PTPRN in lung cancer, especially in LUAD." (PMID 34150744, 2021). "To elucidate whether PTPRN affected metastasis of lung cancer, we evaluated the expression level of PTPRN in TCGA datasets." (PMID 34150744, 2021). "The TCGA RNA Seq data demonstrated that PTPRN was significantly overexpressed in lung cancer compared with noncancerous tissue samples." (PMID 34150744, 2021).
lymph-node metastasis (1 paper, 2021). "Besides, PTPRN was highly expressed in NSCLC patients with distant metastasis and lymph-node metastasis compared with non-metastatic NSCLC patients." (PMID 34150744, 2021).
pancreatic adenocarcinoma (1 paper, 2022). "High PTPRN expression was found to be favorable for survival in pancreatic adenocarcinoma patients." (PMID 35361846, 2022).
temporal lobe epilepsy (1 paper, 2024). A localization-related (focal) form of epilepsy characterized by recurrent seizures that arise from foci within the temporal lobe, most commonly from its mesial aspect. "In this study, we employed weighted gene co‐expression network analysis (WGCNA) and identified the protein tyrosine phosphatase receptor type N (PTPRN) as a regulator of intrinsic neuronal excitability in temporal lobe epilepsy (TLE) patients and TLE rodent models." (PMID 38874331, 2024). "In this study, a new ubiquitin ligase adaptor, protein tyrosine phosphatase receptor type N (PTPRN), is identified as a regulator of intrinsic neuronal excitability in the context of temporal lobe epilepsy." (PMID 38874331, 2024).
tumor (13 papers, 2015 to 2026). "Tumors with low PTPRN expression also exhibit higher tumor mutation burden (TMB) and increased immune cell infiltration compared to those with high PTPRN levels." (PMID 41543046, 2026). "Some tumor-infiltrating lymphocytes are independent predictors of cancer survival, and thus, we investigated the association of PTPRN expression and immune infiltration levels in LGG." (PMID 35741647, 2022). "The tumor mutational burden (TMB) score in the low PTPRN expression group was significantly higher than that in the high PTPRN expression group (p=0.013), with a large degree of tumor immune cell infiltration." (PMID 34976783, 2021). "Finally, GSEA showed that signaling pathways, mainly associated with tumor microenvironment and immune cells, were significantly enriched in PTPRN high expression." (PMID 35741647, 2022). "Like TMEM59L, PTPRN was downregulated in tumor tissues compared to normal tissues, yet high PTPRN expression was associated with poor survival in CRC patients." (PMID 41543046, 2026). "A xenograft model in nude mice validated the TMEM59L/PTPRN axis on tumor growth, stemness, and EMT markers." (PMID 41543046, 2026). "We also investigate the relationship between PTPRN expression and tumor-infiltrating immune cells in LGG." (PMID 35741647, 2022). "We implemented it by selecting PTPRN expression levels that were positively correlated with tumor purity." (PMID 35741647, 2022). "Here, we used TCGA LGG data to analyze the expression level of PTPRN in both tumor and normal tissues." (PMID 35741647, 2022). "Univariate analysis revealed that the advanced pathologic stage (III–IV), tumor stage (T3–T4), regional lymph node (N1–N3), metastasis (M1), and high PTPRN expression were relevant to remarkably shorter OS in LUAD patients." (PMID 34150744, 2021). "In our experiment, PTPRN facilitated N-cadherin and Snail expression and inhibited E-cadherin expression, leading to tumor invasion and metastasis." (PMID 34557405, 2021). "Gene-set enrichment analysis and computational resource were used to analyze the correlation between PTPRN and different tumor-infiltrating immune cells (TIICs)." (PMID 34150744, 2021). "The data of 534 LUAD tumor tissue samples were downloaded from TCGA and divided into high and low expression by the median expression of PTPRN." (PMID 34150744, 2021). "In addition, there was a large degree of tumor immune cell infiltration in LGG patients with high PTPRN expression." (PMID 35741647, 2022). "In addition, the key pathways in LGG that were regulated by PTPRN are possibly tumor microenvironment and immune cells." (PMID 35741647, 2022). "PTPRN could be an independent prognostic factor and correlates with tumor immune infiltration in LGG." (PMID 35741647, 2022). "PTPRN knockdown decreased tumor growth in a mouse xenograft model." (PMID 34557405, 2021). "The tumor volume of PTPRN knockdown mice was significantly decreased." (PMID 34557405, 2021). "According to the results of CIBERSORTx and GEPIA, these findings indicated that PTPRN might play a key role in regulating T cells, macrophage, neutrophils, mast cells, and NK cells of the tumor-infiltrating immune environment." (PMID 34150744, 2021). "Silencing of TMEM59L expression enhanced the inhibitory effect of 5‐FU on tumor growth in mice with CRC, while overexpression of PTPRN reversed the impact of TMEM59L silencing on tumor growth." (PMID 41543046, 2026). "The targets identified by the tumor vs tumor comparisons (EMX2, PTPRN, SCG5) required a representative cohort for ROC analysis; these three genes concern only UCEC and PAAD tumors." (PMID 35361846, 2022). "For example, BCL9L, P2RX6, RER1, EFNA2, CASK, CERCAM, and PTPRN were demonstrated to promote EMT, metastasis, and invasion of tumor cells." (PMID 35586092, 2022).
tumor (continued). "In our study, results demonstrated that overexpression of PTPRN attenuated the effect of TMEM59L silence on ROS combined with DNA damage, cell proliferation, apoptosis, metastasis, and cancer stem cells marker in CRC cells and mice bearing CRC tumor." (PMID 41543046, 2026). "However, effects of Tyrosine phosphatase receptor type N (PTPRN) on the progress of LGG and its correlation with tumor infiltration are unclear." (PMID 35741647, 2022). "We identified five genes (ITGA5, MMP9, PTPRN, PTX3, and STX1A) that could significantly affect the OS rate of patients, and the difference between the tumor group and the normal group was statistically significant." (PMID 33767729, 2021). "Tumor size was significantly increased in the PTPRN overexpression group compared with negative control." (PMID 34150744, 2021). "There was a large degree of tumor immune cell infiltration, including M0 macrophages, M2 macrophages, activated mast cells, neutrophils, and resting memory CD4 T cells, in patients with GBM and high PTPRN expression." (PMID 34976783, 2021). "As can be seen, the genes GLTP and PTPRN present an underexpression in tumour tissue, so attacking it through inhibitor drugs will not produce a positive consequence when slowing tumour development." (PMID 32640984, 2020). "However, the role of PTPRN in LGG is still unknown, especially its role in the regulation of tumor microenvironments." (PMID 35741647, 2022). "For PTPRN and SCG5 expression, PAAD was compared to ESCA, since it was the closest cohort in terms of size (no tumor with a similar site of origin to PAAD was included in this study)." (PMID 35361846, 2022).
cancer (10 papers, 2015 to 2026). A tumor composed of atypical neoplastic, often pleomorphic cells that invade other tissues. "The protein encoded by PTPRN is a member of the protein tyrosine phosphatase family and may be involved in cancer initiation and progression." (PMID 30382873, 2018). "PTPRN is a gene that encodes the protein tyrosine phosphatase receptor type N, a 105.8-kDa protein from the tyrosine phosphatase (PTP) family responsible for signaling related to cancer initiation and progression." (PMID 34976783, 2021). "Some of the LSA genes have been shown to be overexpressed in advanced cancers and be associated with unfavorable clinical outcomes such as SOX11, PTPRN, PNCK and HMGA2." (PMID 28427185, 2017). "We also explored the correlation between PTPRN expression and cancer immune infiltration by TIMER." (PMID 35741647, 2022). "Then, the GSE46531 dataset and the Genomics of Drug Sensitivity in Cancer (GDSC) database were used to examine the relationship between sensitivity radiotherapy (RT) and chemotherapy for GBM and expression of PTPRN and RIM-BP2." (PMID 34976783, 2021). "In contrast to PTPN23, the dysregulation of PTPRN was not significant with CNVs across cancer types." (PMID 36341348, 2022).
PTPRN also shares sentences with these, for which no sentence is quoted: Autoimmunity (17 papers); type 2 diabetes (10); insulinoma (7); MODY (5); Hyperglycemia (4); autoimmune disease (3); autoimmune thyroid disease (3); Obesity (3); autoimmune polyendocrinopathy (2); Impaired glucose tolerance (2); systemic lupus erythematosus (2); thyroiditis (2); acanthosis nigricans (1); Arthritis (1); autoimmune Addison’s disease (1); candidiasis (1); celiac disease (1); COVID-19 (1); dermatomyositis (1); diabetic ketoacidosis (1); female infertility (1); gastric cancer (1); gestational diabetes mellitus (1); glucosuria (1); Graves disease (1); hearing loss (1); Hypertension (1); hypophysitis (1); hypopituitarism (1); idiopathic type 1 diabetes (1).
A further 18 diseases each share a sentence with PTPRN in 1 paper.